CASP6 (caspase 6)
Diseases named in the same sentence as CASP6 in open-access papers (continued):
Sharing a sentence is not in itself a finding about the gene and the disease.
Cognitive impairment (continued). "Future long-term prophylactic treatment studies may enlighten us to the effects of NWL-117 in the context of age and Casp6-dependent cognitive impairment and allow proper identification of target engagement." (PMID 28241839, 2017). "We did not determine whether other caspases are activated downstream of Casp6 in our mouse model and it remains a possibility that the inhibition of other caspases such as Casp4, 8, 9, and 10 additionally contributed to the improvement of cognitive deficits mediated by the over-expression of Casp6." (PMID 28241839, 2017). "Only one other Casp6 inhibitor, ED11, was shown to be brain permeable and have a significant effect against behavioral and cognitive deficits in an Huntington’s mouse model." (PMID 28241839, 2017). "In individuals without cognitive impairment, active caspase-6 is present only in the regions where NFTs first appear: hippocampal CA1 and the entorhinal cortex." (PMID 38114762, 2024). "To assess whether Casp6 cleavage of Tau contributes to Tau pathology and Casp6-mediated age-dependent cognitive impairment, we generated transgenic knock-in mouse models that conditionally express full-length human Tau (hTau) 0N4R only (CTO) or together with human Casp6 (hCasp6) (CTC)." (PMID 33649324, 2021). "Tau fragments cleaved by caspase-6 at amino acids 421 (tauΔD421), as well as active caspase-6, are present in pre- and mature NFTs composed mainly of tau filaments in the patients’ brains with mild cognitive impairment (MCI) or early stage of AD, while absent in the non-AD brains." (PMID 38114762, 2024).
colon carcinoma (12 papers, 2007 to 2025). "Here, we investigated the role of Casp6 in inflammation-associated azoxymethane/dextran sulfate sodium (AOM/DSS) colon cancer in Casp6-overexpressing and -deficient mice." (PMID 25470254, 2014). "Rare mutations of the CASP6 gene have been observed in human colon cancers." (PMID 25470254, 2014). "We have further shown the loss of active Casp6 in less well-differentiated colon cancer tissues." (PMID 24265764, 2013). "Our data suggested that Caspase‐6 activity was required for GSDMC activation in colon cancer both in vitro and in vivo." (PMID 40213993, 2025). "Astonishingly, we investigated the results of sequencing obtained after co-culture of F.n with colon cancer cell lines and determined that the expression of CASP6 was significantly decreased in both HCT116 and HT29 cell lines." (PMID 35937993, 2022). "The IC50 of NWL vinyl sulfone small molecule caspase inhibitors were determined on Caspase-1 to 10, and Caspase-6-transfected human colon carcinoma HCT116 cells." (PMID 28241839, 2017). "Methylene blue, and derivatives, azure A and azure B competitively inhibited recombinant Caspase-6 (Casp6), and inhibited Casp6 activity in transfected human colon carcinoma cells and in serum-deprived primary human neuron cultures." (PMID 26400108, 2015). "Consistent with increased Casp6 expression and activity in human colon cancers, the AOM/DSS-induced colon cancers in mice expressed higher levels of Casp6 mRNA, protein and activity compared to normal adjacent colon tissues." (PMID 25470254, 2014). "Nevertheless, the increased Casp6 gene expression and activity in colon tumors is likely affecting colon physiology." (PMID 25470254, 2014). "In situ hybridization analyses using C57BL/6 ApcMin/+ colon tumor samples also validated that Wif, Tesc, Spock2 and Casp6 were strongly expressed in dysplastic cells of the tumors (data not shown)." (PMID 17615082, 2007). "Thus, our data revealed a new mechanism of GSDMC activation by Caspase‐6 to induce colon cancer cell pyroptosis under Hypoxia and low‐glucose conditions, which was different from Caspase‐8 mediated GSDMC activation in breast cancer." (PMID 40213993, 2025). "Related studies have shown that on human colon cancer HT-29 cells, diosgenin promotes cell apoptosis in a way of repressing Bcl-xl expression, an antiapoptotic protein, and promoting the phosphorylation and the activation of Caspase-6, an apoptotic protein." (PMID 35698571, 2022). "Previous studies have shown that SCU could induce apoptosis of colon cancer cells by enhancing caspase-6 activity." (PMID 29962947, 2018). "Here, our microarray and qPCR results indicated a greater than two-fold up-regulation of caspase-6 mRNA in shSep15 cells, which may be an important apoptotic signaling event in colon cancer cells." (PMID 25886253, 2015). "Casp6 mRNA levels increased 2 fold (p<0.05) in colon tumors compared to adjacent normal tissues." (PMID 25470254, 2014). "Furthermore, others have reported rare mutations of Casp6 in human colorectal cancers and an effect of Casp6 on apoptosis and metastasis of colon cancer cell lines." (PMID 25470254, 2014). "We found that Casp6 expression and activity were increased in colon tumors of Wild-Type (WT) mice." (PMID 25470254, 2014). "Together, these results indicate that Casp6 mRNA, protein and activity levels are increased in AOM/DSS-induced colon tumors." (PMID 25470254, 2014).
colon carcinoma (continued). "Increased human Casp6 or absence of Casp6 expression in mice colon epithelial cells did not change colonic tumor multiplicity, burden or distribution." (PMID 25470254, 2014). "We found that Caspase‐6, but not Caspase‐8, mediated OGD‐induced GSDMC activation in colon cancer cells." (PMID 40213993, 2025).
glioma (9 papers, 2018 to 2024). A benign or malignant brain and spinal cord tumor that arises from glial cells (astrocytes, oligodendrocytes, ependymal cells). "Further analysis of CASP6 expression datasets obtained from the CGGA, REMBRANDT, TCGA, GSE4290 databases showed that higher CASP6 expression was associated with the grade of glioma." (PMID 36119521, 2022). "We propose that detecting CASP6 expression combined with clinical features might improve the diagnostic accuracy in patients with glioma." (PMID 36119521, 2022). "Furthermore, univariate and multivariate Cox analyses identified CASP6 expression as an independent prognostic risk factor for glioma patients." (PMID 36119521, 2022). "These analyses identified CASP6 as one of the glioma-associated PRDEGs." (PMID 36119521, 2022). "Their research revealed CASP6 overexpression in glioma, primarily implicating it in immune responses and antigen processing." (PMID 39184045, 2024). "CASP6 expression was inversely correlated with overall survival and disease progression in glioma patients." (PMID 39184045, 2024). "Caspase-6 (CASP6), a critical protein in the pyroptosis pathway, presents fluctuating relevance in glioma prognosis." (PMID 39184045, 2024). "Increasing evidence has revealed that CASP6 is involved in carcinogenesis and tumor progression, such as glioma and colorectal cancer." (PMID 36882663, 2023). "It is notable that the genes were immune-related genes, according to MSigDB, and SLC11A1 was reported to be associated with the microenvironment in CRC and a similar result was found for CASP6 in gliomas." (PMID 37920710, 2023). "In ROC curves based on the 3-, and 5-year OS, groups of patients with glioma exhibiting higher CASP6 expression were separated from those with glioma of lower CAP6 expression, with AUC values ranging from 0.668 to 0.809." (PMID 36119521, 2022). "Our results showed that CASP6 was a significant biomarker to predict the prognosis of patients with glioma." (PMID 36119521, 2022). "CCK-8 and colony forming assays demonstrated that CASP6 is highly related to the proliferation of glioma." (PMID 36119521, 2022). "CCK-8 and colony formation assays were conducted to evaluate the effects of knocking down CASP6 expression on glioma cell proliferation." (PMID 36119521, 2022). "CASP6 expression in normal human astrocytes was lower than that in human glioma cell lines (U251 and T98G), as confirmed by qRT-PCR." (PMID 36119521, 2022). "Quantitative real-time reverse transcription PCR and western blotting were carried out to confirm the different expression levels of CASP6 between human astrocytes and glioma cell lines (U251 and T98G)." (PMID 36119521, 2022). "ROC analysis demonstrated that CASP6 expression was a reliable marker to predict clinical outcomes in patients with glioma." (PMID 36119521, 2022). "To explore the prognostic significance of CASP6 in patients with glioma, we chose the CGGA database for further analyses." (PMID 36119521, 2022). "The accuracy of CASP6 expression to predict the 3-year-OS and 5-year-OS of patients with glioma was evaluated using a ROC curve." (PMID 36119521, 2022). "In both CGGA and TCGA datasets, glioma sample group with increased levels of CASP6 expression exhibited a higher immune score than the group with decreased CASP6 expression." (PMID 36119521, 2022). "The immunohistochemical images obtained from the HPA showed that CASP6 expression was lower in normal brain tissue than in glioma tissue." (PMID 36119521, 2022). "Collectively, these results demonstrated that the expression of CASP6 correlated positively with glioma cell proliferation." (PMID 36119521, 2022). "However, the association between CASP6 and prognosis of glioma patients remains unclear." (PMID 36119521, 2022). "To explore the effects of CASP6 on the brain immune microenvironment of patients with glioma, we used several deconvolution algorithms." (PMID 36119521, 2022).
glioma (continued). "We determined the role of CASP6 in the tumorigenesis of glioma by knocking down CASP6 in U251 and T98G cell lines." (PMID 36119521, 2022). "In vitro, CASP6 was verified as an oncogene in glioma, and CASP6 inhibition prevented glioma cell proliferation." (PMID 36119521, 2022). "In our study, patients with glioma with lower CASP6 expression presented a better response to immunotherapy." (PMID 36119521, 2022). "The pyroptosis-related DEGs (PRDEGs) were extracted from each dataset, and CASP6 was found to be aberrantly expressed in glioma." (PMID 36119521, 2022). "Based on the median CASP6 expression level, glioma samples were sub-classified into a group with high CASP6 expression levels and a group exhibiting low levels of CASP6 expression." (PMID 36119521, 2022). "Kaplan-Meier survival curve showed that patients with glioma with lower CASP6 had a longer OS (P < 0.0001)." (PMID 36119521, 2022). "Clinical characteristics of 651 patients with primary glioma in the CGGA dataset according to CASP6 expression." (PMID 36119521, 2022). "The bioinformatics analysis showed that CASP6 expression increased with the increasing degree of malignancy of glioma." (PMID 36119521, 2022). "Consistently, analysis of TCGA and the REMBRANDT cohorts demonstrated that patients with glioma exhibiting lower CASP6 expression levels had longer survival (P < 0.0001)." (PMID 36119521, 2022). "To investigate the role of CASP6 in the TIME of glioma, we evaluated the immune score and immune infiltration in glioma samples with low or high CASP6 expression levels, respectively." (PMID 36119521, 2022). "In the present study, we identified the PRDEG CASP6 as a biomarker for glioma." (PMID 36119521, 2022). "The pyroptosis-related gene CASP6 might represent a sensitive prognostic marker for patients with glioma and might predict their response of immunotherapy and temozolomide therapy." (PMID 36119521, 2022). "Our findings revealed that the CASP6 could play a role in determining therapeutic strategies for patients with glioma." (PMID 36119521, 2022). "We found that CASP6 was overexpressed in glioma samples and in glioma cell lines." (PMID 36119521, 2022). "Furthermore, we found that CASP6 expression level was correlated with prognosis of glioma patients, and outcomes of chemotherapy and immunotherapy." (PMID 36119521, 2022). "Finally, the abnormal expression of CASP6 in gliomas was verified using an external database and cell experiments." (PMID 36119521, 2022). "CASP6 expression in patients with glioma correlated negatively with overall survival." (PMID 36119521, 2022). "In addition, we performed experimental validation of aberrant CASP6 expression in patients with different grades of glioma." (PMID 36119521, 2022). "To further confirm the predictive value of CASP6 expression as a new prognostic biomarker for glioma, we conducted a meta-analysis, which showed that based on its HR and 95% CI (2.18 and 1.24–3.82, respectively), CASP6 expression is a robust prognostic indicator." (PMID 36119521, 2022). "Notably, TMZ presented a better therapeutic response in patients with glioma with high CASP6 expression." (PMID 36119521, 2022). "Finally, in vitro functional experiments showed that knockdown of CASP6 inhibited the proliferation of glioma cells." (PMID 36119521, 2022). "Accordingly, similar results were obtained from analysis of the TCGA and REMBRANDT databases Taken together, these data indicated that CASP6 may represent a potential prognostic biomarker for patients with glioma." (PMID 36119521, 2022). "In addition, we analyzed the biological functions of CASP6 in glioma and found that CASP6 was involved in the immune microenvironment and the infiltration of immune cells." (PMID 36119521, 2022). "Our findings suggest that CASP6 is a marker to predict the prognosis of glioma patients and might be a potential target to treat glioma." (PMID 36119521, 2022).
glioma (continued). "Indeed, stratification survival analysis demonstrated the good predictive role of CASP6 expression in glioma." (PMID 36119521, 2022). "Furthermore, the HPA immunohistochemistry images showed that high-grade glioma tissues contained higher levels of CASP6 than low-grade glioma tissue." (PMID 36119521, 2022). "Taken together, these results indicated that CASP6 may play a role in regulating in immune cell infiltration in glioma." (PMID 36119521, 2022). "In agreement, univariate and multivariate Cox analysis showed that CASP6 expression could be a predictor of prognosis in patients with glioma." (PMID 36119521, 2022). "Together, these results identified CASP6 as a candidate biomarker in glioma." (PMID 36119521, 2022). "However, the status of CASP6 as a PRG in glioma has been rarely reported, therefore, the role of CASP6 in glioma was unclear." (PMID 36119521, 2022). "However, the effects of CASP6 on glioma pyroptosis and its mechanism need further investigation." (PMID 36119521, 2022). "Finally, in vitro experiments showed that CASP6 knockdown inhibited glioma proliferation." (PMID 36119521, 2022). "In addition, CASP6 expression correlated positively with the degree of glioma progression." (PMID 36119521, 2022). "Immunohistochemical images of normal brain tissue, low-grade glioma, and high-grade glioma acquired from the HPA, confirmed that the protein level of CASP6 increased with increasing tumor grade." (PMID 36119521, 2022). "Thus, CASP6 might represent a potential target in the treatment of glioma." (PMID 36119521, 2022). "In our study, the results showed that flubendazole increased apoptosis among glioma cells via downregulating the expression of Bcl-2, Bcl-xl, and PARP-1, while upregulating the expression of caspase-3, caspase 6 and caspase-9." (PMID 29531815, 2018).
breast carcinoma (8 papers, 2019 to 2025). "Here, we report that in hot breast cancer tissue, central apoptotic marker proteins such as the cleaved version of the initiator caspase 9, the cleaved effector caspase 6 and Bax were upregulated." (PMID 36139700, 2022). "Another pathway, such as caspase-6 or 7, can also induce apoptosis in T47D breast cancer cells." (PMID 31031969, 2019). "Although the cleavage of GSDMC by Caspase‐8 was reported in breast cancer, conditional deletion of Caspase‐8 in intestinal epithelial cells dramatically enhanced GSDMC activation rather than inhibiting it, likely due to increased Caspase‐6 activity." (PMID 40213993, 2025).
cognitive decline (7 papers, 2016 to 2024). "We do know that overexpression of caspase-1, caspase-2, caspase-3, caspase-6, and caspase-8 is linked to Aβ accumulation and cognitive decline in mouse models and patients with neurodegenerative diseases." (PMID 39625520, 2024). "In conclusion, these data support the possibility that the Casp6 activity in the AON of the olfactory bulb reflects degeneration in the ERC and suggest that Casp6 activity in the olfactory bulb could represent degeneration associated with cognitive decline and early AD." (PMID 27931265, 2016). "Methylene blue exhibited this effect by inhibiting caspase-6 and caspase-6-mediated neurodegeneration and neuroinflammation, which could potentially benefit patients suffering from cognitive decline in AD, if translatable to human studies." (PMID 38135855, 2024). "In addition, the inhibition of caspase‐1 has been shown to inhibit cognitive decline in mouse models of AD by reducing the production of active caspase‐6." (PMID 36579934, 2023). "Next, we tested whether caspase-6 KO would inhibit the cognitive decline seen in 5xFAD mice." (PMID 32050445, 2020).
gastric cancer (7 papers, 2011 to 2023). A primary or metastatic malignant neoplasm involving the stomach. "Overall, 2% of 150 colonic or gastric cancers are associated with CASP6 mutations, and expression of caspase-6 in gastric cancer tissues is decreased." (PMID 34862482, 2022). "Caspase-6 mutations are associated with reduced caspase-6 expression in colon and gastric cancer." (PMID 36976231, 2023).
Parkinson disease (7 papers, 2012 to 2025). A progressive degenerative disorder of the central nervous system characterized by loss of dopamine producing neurons in the substantia nigra and the presence of Lewy bodies in the substantia nigra and locus coeruleus. "More recently caspase-6 has also been implicated in Parkinson's disease as the neuroprotective function of DJ-1 protein is dependent on caspase-6 proteolysis." (PMID 22253931, 2012).